PACRGL (parkin coregulated like)
Synonyms: C4orf28; MGC29898
Tractability: PROTAC: ubiquitination databases record sites on it.
Gene: Protein-coding gene on chromosome 4 (20,696,282 to 20,752,907, forward strand). Ensembl gene ENSG00000163138.
Subcellular location (Human Protein Atlas): Nucleoplasm; Vesicles
Gene Ontology:
Molecular function: protein binding
Genetic constraint (gnomAD): Loss-of-function variants: 22 observed, 20.91 expected, observed/expected ratio (o/e) 1.05, 90% interval 0.75 to 1.5. The upper end of that interval is the gene's LOEUF score, 1.5, which puts it in group 6 of 6, group 1 being the genes least tolerant of losing a copy. Missense variants: 233 observed, 212.6 expected, observed/expected ratio (o/e) 1.1, 90% interval 0.98 to 1.22. Synonymous variants: 98 observed, 79.21 expected, observed/expected ratio (o/e) 1.24, 90% interval 1.05 to 1.46.
Homologues: Orthologues: chimpanzee PACRGL (99% identical), macaque PACRGL (90% identical), mouse 5730480H06Rik (89% identical), pig PACRGL (88% identical), guinea pig PACRGL (86% identical), rat Pacrgl (83% identical), dog PACRGL (67% identical), tropical clawed frog pacrgl (56% identical). Paralogues in human: PACRG (25% identical).
Diseases named in the same sentence as PACRGL in open-access papers:
PACRGL is named in the same sentence as 1 disease in open-access papers, as found by Europe PMC text mining. Sharing a sentence is not in itself a finding about the gene and the disease. The quoted sentences say what the papers report.
cancer (1 paper, 2022). A tumor composed of atypical neoplastic, often pleomorphic cells that invade other tissues. "The expression levels of LIAS had a positive correlation with the expression levels of CTD-2366F13.1 (R = 0.47, p < 0.001), RAD17 (R = 0.48, p < 0.001), OCIAD1 (R = 0.49, p < 0.001), PACRGL (R = 0.49, p < 0.001), MRPS27 (R = 0.49, p < 0.001), and THAP9 (R = 0.49, p < 0.001) in pan-cancer." (PMID 35982953, 2022).